IL6 (interleukin 6)
Diseases named in the same sentence as IL6 in open-access papers (continued):
Sharing a sentence is not in itself a finding about the gene and the disease.
myocardial ischemia (continued). "It has been shown that puerarin reduced the mRNA and protein levels of Tumor necrosis factor-α (TNF-α), interleukin 6 (IL-6), and IL-1β in a mouse model of myocardial ischemia/reperfusion (MI/R) injury, inhibited NLRP3 inflammasome and protected the heart." (PMID 36353499, 2022). "Myocardial ischemia significantly increased the mRNA and protein expressions of IL-6, IL-8, TNFα, TGF-β1, MMP2, MMP9, and c-Myc in cMSCs." (PMID 36056383, 2022). "In such a scenario, the endogenous IL-6 production at the onset of cardiac ischemia is low and quantitatively ineffective in the induction of cardiac dedifferentiation that protects cardiomyocytes from ischemic damage." (PMID 35101092, 2022). "Similar to our findings, MT-induced downregulation of TNF and IL-6 has been also identified in a rabbit model of myocardial ischemia." (PMID 35495036, 2022). "In this observational study, consecutive patients referred for elective coronary angiography due to stable chest pain/myocardial ischemia had IL-6 measured immediately before the procedure." (PMID 36028849, 2022). "Most importantly, we demonstrated that injury-responsive gene, WT1, was linked to upregulation of IL-6, which in turn mediated the regenerative activity of ADSC via promoting cardiac dedifferentiation at the onset of cardiac ischemia." (PMID 35101092, 2022). "It is known that SIRT1 can inhibit the expression levels of p65, TNF-α, IL-1β, IL-6, iNOS, and other markers related to oxidative stress by regulating the NF-κB pathway, thus playing a role in myocardial ischemia-reperfusion." (PMID 34868528, 2021). "M1 macrophages expressed TNF-α, iNOS, IL-1β, and IL-6, which induced a strong proinflammatory reaction and contributed to myocardial ischemia-reperfusion injury." (PMID 34094602, 2021). "Mice were exposed to I/R injury with intravenous injection of IL-6 at a dose of 10 μg/kg or vehicle 15 min before the onset of myocardial ischemia." (PMID 33428604, 2021). "During myocardial ischemia-reperfusion, cardiomyocytes release IL-6, which induces neutrophils and cardiomyocytes to express CD11b/CD18 and intercellular adhesion molecule-1 (ICAM-1), thereby damaging the myocardium." (PMID 34504432, 2021). "Another report showed the reduced release of TNF-α, IL-1β, and IL-6 in myocardial ischemia/reperfusion (MI/R) rats treated with MLB." (PMID 33014451, 2020). "Myocardial ischemia/reperfusion can cause an increase in the levels of cytokines such as TNF-α, IL-6, and IL-1β." (PMID 30944548, 2019). "Such an increased coagulation, when associated with microvascular thrombosis, is then a possible mechanism through which IL-6 can increase infarct size after myocardial ischemia–reperfusion." (PMID 26935770, 2016). "TNF-α, IL-1, IL-6, and IL-8 after myocardial ischemia began to produce and release TNF-α, which exacerbates myocardial injury via activation of neutrophils and endothelial cells." (PMID 26941825, 2016). "We examined the role of IL-6 in the temporal development of cardiac ischemia–reperfusion injury employing a closed-chest I/R model." (PMID 26935770, 2016). "It has been reported that hearts from TLR4-defctive mice and TLR4 knockout mice display attenuated NF-κB activation and reduced production of pro-inflammatory cytokine (TNF-α, IL-1β and IL-6) following myocardial ischemia with a short period of reperfusion." (PMID 25823011, 2015). "The proinflammatory cytokine interleukin-6 and biochemical indices of cardiac ischemia (creatine kinase, and troponin I) were comparable between both groups." (PMID 26021999, 2015). "One study explained that treatment with DITPA attenuates the acute inflammatory response following myocardial ischemia by reducing inflammatory mediators, IL-6." (PMID 24167735, 2013).
myocardial ischemia (continued). "Although multiple cardiac cell types have been implicated in IL-6 formation during cardiac ischemia and reperfusion, this research systematically compared cardiomyocytes and noncardiomyocytes at both mRNA and protein levels for IL-6 measurement." (PMID 40048077, 2025). "In the treatment of rats, a model of myocardial ischemia, the alcoholic extract of Tiekuaizi reduced the expressions of interleukin-18 (IL-18), interleukin-6 (IL-6), and TNF-α and was able to protect against myocardial cell injury produced by inflammatory cell infiltration." (PMID 39830344, 2024). "Following myocardial ischemia, cardiomyocytes would experience irreversible necrosis from hypoxia, followed by the infiltration of inflammatory cells and the release of pro-inflammatory factors like IL-6." (PMID 38271442, 2024). "The GXDSF significantly reduced myocardial ischemia area, reduced myocardial structural injury, decreased the levels of interleukin (IL-1β, IL-6) in serum, decreased the activity of myocardial enzymes, increased the activity of superoxide dismutase (SOD), and reduced glutathione in rats with MIRI." (PMID 37098925, 2023). "Additionally, IL6 production is enhanced from the myocardium in states of cardiac ischemia, congestive heart failure, and congenital heart disease in humans and mice." (PMID 36977223, 2023). "Furthermore, valsartan has been shown to inhibit cardiac TNF-α, IL-6, and IL1β production in a rat model of myocardial ischemia." (PMID 35163209, 2022). "(ii) Is IL-6 involved in the protective role of HIF2α in myocardial ischemia-reperfusion?" (PMID 33428604, 2021). "After a 30-min exposure to myocardial ischemia followed by 24 h of reperfusion, we found significantly reduced myocardial infarct sizes and troponin I serum levels in the mice treated with recombinant IL-6 compared with those treated with vehicle." (PMID 33428604, 2021). "In addition, in the animal model, it was found that the serum IL-6 in mice increased significantly within 6 h after myocardial ischemia/reperfusion." (PMID 34504432, 2021). "Rosmarinic acid has been shown to protect against inflammation and myocardial cell apoptosis during myocardial ischemia/reperfusion injury by activating peroxisome proliferator-activated receptor γ and inhibiting the production of inflammatory cytokines, such as IL-6, TNF-α, and C-reactive protein." (PMID 34484404, 2021). "Given that IL-6 is a marker of cardiac ischemia, XBJ and C0127s may improve circulation in the cardiac function of septic mice." (PMID 33986658, 2020). "Myocardial ischemia/reperfusion can cause cytokines such as TNF-α, IL-6, and IL-1β." (PMID 31249649, 2019). "Additionally, in isoprenaline-induced rats, Granule of BU-XIN RUAN-MAI ameliorated myocardial ischemia by downregulating the inflammatory factor levels of IL-6, IL-1β, and TNF-α." (PMID 31949464, 2019). "Therefore, high concentrations of IL-6 in BC patients may promote the occurrence of coronary atherosclerosis, myocardial ischemia, and MI." (PMID 40251177, 2025). "This study demonstrated that h-cTnT and IL-6 are significantly correlated, suggesting an association between ongoing inflammation and h-cTnT concentrations in HD patients without acute symptoms of myocardial ischemia." (PMID 38271442, 2024). "Our findings showed that patients with a history of myocardial ischemia showed high expression of IMA, H-FABP, and the inflammatory factors IL-1β, TNF-α, and IL-6." (PMID 40236258, 2025). "The primary constituent gastrodin mitigates myocardial ischemia–reperfusion injury through increased coronary flow, the suppression of endothelin-1 and pro-inflammatory cytokines (TNF-α/IL-6), oxidative stress reduction, and apoptosis inhibition." (PMID 40723404, 2025). "For example, netrin-1 overexpression has been shown to suppress IL-6 and COX-2 expression, reduce Th1/Th2/Th17 cytokines from CD4+ T cells, and improve outcomes in models of kidney and cardiac ischemia." (PMID 40728980, 2025).
myocardial ischemia (continued). "In canine experimental cardiac ischemia-reperfusion, mast cells primarily released TNF-α, which then exacerbated myocardial inflammation and cardiac injury by upregulating IL-6 in infiltrating leukocytes and initiating the cytokine cascade." (PMID 38392268, 2024). "Myocardial ischemia–reperfusion induces ROS synthesis, triggering the release of proinflammatory factors (such as TNF-α, IL-6, IL-1β)." (PMID 38541636, 2024). "In patients with myocardial ischemia, especially in the acute phase, pro-inflammatory biological factors such as hsCRP, tumor necrosis factor-α (TNF-α), interleukin-6 (IL-6), and interleukin-1β (IL-1β) were significantly increased." (PMID 35252378, 2022). "We introduce new data showing that acute myocardial ischemia and reperfusion injury (IR) increase TNF-a, IL-6, and MMP-9 levels in the LV and renal cortex." (PMID 33782857, 2022). "Compared with the sham operation group, the myocardial ischemia-reperfusion injury group showed significant increases in TLR4, NF-KB, IL-1β, TNF-α, and IL-6." (PMID 34093716, 2021). "In an animal model of myocardial ischemia, the expression of EGFR in alveolar macrophages was up-regulated, and contributed to the expression of proinflammatory cytokines (such as TNF, IL-6, IL-1β), chemokines (such CXCL2/MIP-2, MCP-1, and CCL3) and iNOS." (PMID 35095926, 2021). "It is also reported to attenuate myocardial ischemia–reperfusion by regulating the PI3K/Akt signaling pathway and the subsequent reduction of inflammatory factors, including IL-6, IL-18, and TNF-α." (PMID 28529539, 2017). "The formation of IL-6 is related to early incipient myocardial ischemia and contact of cells with artificial and non-endothelialized surfaces, whereas IL-8 production is mainly explained by the shear stress of the perfusion system." (PMID 38903492, 2024). "Research has shown that higher levels of circulatory cytokines such as IL-6, IL-8, and TNF-α are closely related to impaired hemodynamics and may contribute to postoperative myocardial ischemia and deteriorated clinical outcomes after cardiac surgery." (PMID 38807202, 2024). "Besides, myocardial ischemia–reperfusion increased the levels of TNF-α and IL-6 in the serum, and these levels were reduced by OP treatment." (PMID 38589925, 2024). "Interestingly, the levels of IL-6 and the nuclear translocation of NF-κB were both evidently decreased by PAL, one of the most active metabolites of SABP in myocardial ischemia/reperfusion injury." (PMID 36925635, 2023). "Additionally, increased levels of IL-6 increase the incidence of postoperative complications such as ARDS, myocardial ischemia, and low cardiac output syndrome." (PMID 33228727, 2020). "The activation of NF-κB following myocardial ischemia could induce the production of TNF-α by myocardial tissues in addition to regulating the expression of numerous genes, including IL-1β, IL-6, ICAM-l and VCAM-1." (PMID 25667680, 2015). "Thus, upon acute myocardial ischemia and MI, cardiac cells are able to promptly release into circulation not only MIF, also other inflammatory molecules like IL-6." (PMID 24098445, 2013). "We hypothesise that the increase in values of IL-6, hs-CRP and their correlation to leptin in AMI patients could be due to participation of leptin in the signaling cascade after myocardial ischemia." (PMID 22891684, 2012). "The upregulation of IL-6 and the increase in its signaling product hs-CRP suggests the possible involvement of leptin in the signaling cascade through activation of leptin receptor after myocardial ischemia." (PMID 22891684, 2012). "The IL-6 response was not related to either exercise intensity and duration or myocardial ischemia." (PMID 33288784, 2020).
myocardial ischemia (continued). "After 1⁄2 h reperfusion, cardiac IL-6 levels were already significantly elevated in the ischemic part of the heart as compared to the non-ischemic part in WT mice (5.6 ± 1.0 vs 1.7 ± 0.2 μg/mg; n = 6, respectively), indicating IL-6 to be a fast responder to cardiac ischemia (data not shown)." (PMID 26935770, 2016). "Moreover, diltiazem also reduced myocardial ischemia, endothelia dysfunction and inflammatory responses, as indicated by changes in c-TnI, plasma vWF and ET-1 levels, as well as the myocardial protein expression levels of TNF-α and IL-6." (PMID 24137281, 2013). "In this study we have demonstrated that IL-6 is one of the mediating factors that contributes to the development of cardiac infarct size during the early period (<1 day) of reperfusion, following an injurious period of cardiac ischemia in the absence of surgical stress." (PMID 26935770, 2016).
thrombosis (96 papers, 2013 to 2026). "The clearance of alveolar macrophages reverses the elevated circulating IL-6 levels and thrombosis caused by PM2.5 exposure." (PMID 39639885, 2024). "Anti-phosphatidylserine positivity in IgM class was associated with thrombosis, and anti-phosphatidylinositol positivity in IgM class was associated with inflammation, as noticed by elevated levels of IL-6." (PMID 37626797, 2023). "In multivariable analysis, the inflammatory blood marker IL-6 and thrombosis blood markers Fib and tPA were significantly associated with smoking." (PMID 27576214, 2016). "LA was found to be independently associated with thrombosis, Hypoxia and IL6 lead to a severe decrease in PS that might aggravate the thrombosis risk." (PMID 36138306, 2023). "Raised IL-6 levels have been found to be related to recurrent venous thrombosis, with detectable levels of IL-6 associated with a two-fold increase in the risk of venous thrombosis." (PMID 34335591, 2021). "The increase of IL-6 caused by the injury of vascular endothelium could induce a large number of corresponding antibodies to form immune complexes and result in thrombosis." (PMID 31632272, 2019). "When stratified by control, non-thrombosis, and thrombosis groups, IL-6 and TNF-α demonstrated a progressive increase across categories, consistent with a graded inflammatory response." (PMID 40776916, 2025). "Direct IL-6 inhibition attenuates arterial thrombosis in a murine model of endothelial damage and chronic low-grade inflammation." (PMID 40534557, 2025). "In the present investigation, we found that OP effectively suppressed the activation of TLR4/NF-κB and reduced the levels of inflammatory markers such as TNF-α, IL-1β and IL-6 in liver and lung tissues of mice with carrageenan-induced thrombosis." (PMID 40276603, 2025). "Ang-2 induces inflammation (stimulates the IL-6 release), vasculopathy, thrombosis, and coagulopathy." (PMID 40722786, 2025). "Some previous studies have shown higher circulating levels of IL-6 in patients with deep vein thrombosis than in healthy controls." (PMID 39858477, 2025). "The results showed that the neutrophil and lymphocyte count and CRP, D-dimer, IL-6, integrin β1, integrin β2, and integrin β3 levels were all independent predictors of venous thrombosis." (PMID 37998519, 2023). "From this series of experiments, we have characterized the role of IL-6 in two models of VT which replicate clinical venous thrombosis; namely, partial and complete blood stasis." (PMID 36828892, 2023). "The levels of D-dimer, IL-6, integrin β1, integrin β2, and integrin β3 significantly impacted venous thrombosis." (PMID 37998519, 2023). "Deep venous thrombosis and residual thrombus burden correlates with circulating IL-6 levels in humans." (PMID 36828892, 2023). "According to a previous study on deep vein thrombosis, platelet activation is involved in endothelial cells and serum inflammatory factors, with the regulation of p-selectin, GPIIb/IIIa, IL-2, IL-6, and IL-8." (PMID 36851332, 2023). "The relationship between IL-6 and formation of thrombosis was assessed in a study measuring levels of IL-6 in patients with deep vein thrombosis (DVT)." (PMID 37005767, 2023). "We found that the levels of IL-6 increased significantly in patients with arterial thrombosis and AF-related thrombosis during the 2-year follow-up; our results were consistent with the previous findings." (PMID 36211709, 2022). "Wild-type C57BL/6J (WT) and IL-6−/− mice underwent induction of stasis venous thrombosis by ligation of the infrarenal IVC." (PMID 35647566, 2022). "IL-6 was reported to contribute to deep vein thrombosis via induction of hepatic thrombopoietin and dysregulation of miR-338–5p expression." (PMID 35203844, 2022). "Post-IL-6 spike, a vicious cycle of NETosis and thrombosis ensues and sustains illness severity and ARDS." (PMID 34775962, 2021).